BDNF (brain derived neurotrophic factor)
Diseases named in the same sentence as BDNF in open-access papers (continued):
Sharing a sentence is not in itself a finding about the gene and the disease.
dementia (continued). "Indeed, our results provide further information about the involvement of BDNF in dementias and in PD for the implementation of new therapeutic strategies." (PMID 24024214, 2013). "Except for L-DOPA, for which the effect couldn't be discriminated, the differences in BDNF levels in our work remained significant for all dementias after correcting for the effect of various pharmacological treatments." (PMID 24024214, 2013). "In these patients, the higher incidence of dementia typically observed Down's syndrome old subjects, may induce a significant increase of plasma BDNF, as a protective response to prevent learning, memory functions and behavior degeneration." (PMID 20181009, 2010). "Therefore, the increased expression of miR-134 may be accompanied by decreased CREB and BDNF and lead to dementia." (PMID 39061398, 2024). "Exercise can increase the concentration of brain-derived neurotrophic factor, promote nerve regeneration, improve nervous system, so as to improve the brain structure involved in cognition, reduce the degree of dementia in patients with AD and further improve their ability of daily living." (PMID 38882523, 2024). "Therefore, to understand the importance of BDNF in AD, it is necessary to determine whether BDNF Met66 carriage is related to increases in tau and memory decline in the pre-dementia stages of sporadic AD." (PMID 38454193, 2024). "BDNF mRNA expression was found to be reduced in the hippocampus and temporal cortex of individuals with AD, suggesting that BDNF could be involved in progressive neuron atrophy accompanying dementia." (PMID 36830773, 2023). "However, it could also be argued that if antidepressant efficacy is partly mediated by augmenting BDNF then strategies to increase BDNF levels could be an effective approach in dementia where it is lower." (PMID 36621964, 2023). "Earlier detection would facilitate therapy, and this is precisely why the goal of this research was to determine whether a reliable biomarker for the development of dementia can be established through the expression and methylation of BDNF and COMT in peripheral blood." (PMID 36830773, 2023). "Canine cognitive dysfunction (CCD) is an analog of human dementia because the conditions may share similar neuropathologies such as cerebral atrophy, ventricular dilation, reduced vascularity, decreased levels of brain‐derived neurotrophic factor (BDNF) and accumulation of β‐amyloid (Aβ) plaques." (PMID 34495560, 2022). "Studies of animal models reported that the beneficial effect of rTMS may be induced by the upregulation of neurotrophic or growth factors, and rTMS can improve CI in dementia model rats by changing the activity of N-methyl-d-aspartic acid receptor and brain-derived neurotrophic factor (BDNF)." (PMID 36138921, 2022). "Furthermore, it was proposed that MCI represents an early stage in the trajectory of dementia, where peripheral BDNF levels may be increased as a compensatory and neuroprotective strategy in response to various neuronal insults." (PMID 34607976, 2021). "Furthermore, plasma BDNF alone accounted for 19-24% (R2=0.19 to 0.24) of the variance explained in each of the cognitive domains, providing further support for its potentially prominent functions in modulating cognition in preclinical dementia." (PMID 34607976, 2021). "Relatedly, this BDNF genotype may also impact interventions designed to improve or stabilise cognitive function and cognitive reserve, potentially acting as a bulwark against neurodegenerative conditions such as dementia." (PMID 32218234, 2020). "Meanwhile, activation of BDNF-TrkB signaling would facilitate the long-term potentiation and formation of synapses, by triggering phosphorylation and the expression of proteins that are markers of synaptic plasticity, thus lessening the vulnerability to dementia." (PMID 32923448, 2020).
dementia (continued). "However, the presence of a BDNF Met allele does not appear to directly and independently affect an individual’s risk for dementia." (PMID 32218234, 2020). "Additionally, the combined COMT and BDNF risk is also associated with poor executive function in ε4 carriers without dementia." (PMID 30866553, 2019). "HI alters expression of hundreds of genes, including BDNF and amyloid precursor protein both in rodents and humans, which is supposedly part of an acute compensatory protective response, but may lead to dementia in later life." (PMID 29651259, 2018). "Neuromuscular integrity and physical function are typically compromised in aging and dementia patients; thus, whether by stimulation of muscle-related growth factors or an increase in serum BDNF, FST supplementation may act to preserve physical function in the elderly." (PMID 30008787, 2018). "Higher serum BDNF level may protect against the future occurrence of dementia." (PMID 29312105, 2017). "In addition, serum levels of BDNF are also correlated with the severity of dementia." (PMID 28377712, 2017). "The beneficial effect of PA on the aging brain or in dementia is not well explained, but animal studies have revealed activation of adult neurogenesis or increases in plasma levels of the neuroplasticity associated brain-derived neurotrophic factor." (PMID 25884637, 2015). "It is possible that our relatively healthy sample of older adults without dementia at baseline lacked sufficient variability in BDNF to detect associations reported elsewhere, although the serum BDNF range exhibited in our data is consistent with other similar studies." (PMID 24670553, 2014). "Therefore, the involvement of BDNF in dementia has been discussed extensively." (PMID 18184369, 2008). "Compelling evidence indicates a role of brain-derived neurotrophic factor (BDNF) in cognitive functions and dementia." (PMID 41009553, 2025). "Despite these insights, comprehensive studies that concurrently investigate region-specific BDNF methylation, peripheral BDNF mRNA and protein expression, BDNF rs6265 genotype, and neurocognitive profiles from MCI to dementia patients remain rare." (PMID 41009553, 2025). "This was reflected in its stronger AChE-inhibitory activity, increased noradrenaline neurotransmission, the activation of BDNF/CREB signaling, and pronounced anti-apoptotic effects in the cortex and hippocampus of rats with experimental dementia." (PMID 39684486, 2024). "As an upstream regulator of BDNF, the PAI-1/BDNF ratio is proposed as a selective marker of AD patients with full dementia to distinguish from other prodromal AD stages and healthy controls." (PMID 38892118, 2024). "The NfL/BDNF ratio was significantly increased in the SUD group (p < 0.001) and the dementia group (p = 0.010) compared to the control group." (PMID 36674698, 2023). "The impact of substance abuse on plasma concentrations of NfL, BDNF and NfL/BDNF ratio was studied in the total sample using a one-way ANCOVA with “group” (SUD, dementia, and control groups) as a factor and age as a covariate." (PMID 36674698, 2023). "Our results showed that the NfL/BDNF ratio was higher in SUD and dementia patients compared to controls." (PMID 36674698, 2023). "Plasma BDNF levels decreased in the MCI stage and increased in the dementia stage and were affected by age, education, occupation, and sample source." (PMID 36425322, 2022). "On the cellular level, prominent changes of synaptic plasticity with the presence of an increased expression of serum brain‐derived neurotrophic factor (BDNF) after successive rTMS treatment have been observed in rodent models of brain ageing and dementia." (PMID 35912517, 2022). "In dementia rat models, tFUS-induced BBB disruption in the hippocampus increased brain-derived neurotrophic factor (BDNF), early growth response protein 1 (EGR1), and hippocampal neurogenesis, which lead to improved spatial memory." (PMID 35207738, 2022).
dementia (continued). "Developing evidence suggested that decreased brain-derived neurotrophic factor (BDNF) and damaged synaptic plasticity led to dementia." (PMID 35431908, 2022). "Given plasma BDNF’s increased levels in MCI, along with its positive association with hs-CRP, and inverse associations with multiple neurocognitive domains, our data support the hypothesis that increased peripheral BDNF acts as a compensatory mechanism in the preclinical stage of dementia." (PMID 34607976, 2021). "Finally, in older adults possessing gene mutations linked to dominantly inherited AD but without dementia, BDNF Met carriage was associated with more substantial memory decline and hippocampal volume loss, as well as increased cerebrospinal fluid (CSF) tau levels, relative to Val homozygotes." (PMID 32218234, 2020). "In conclusion, the present study indicates that the potential anti-dementia effect of SG-ME would involve the enhancement of cell proliferation and LTP resulting from the activation of BDNF/CREB signaling pathways in neurons." (PMID 33281604, 2020). "Therefore, BDNF may be a potential target for dementia prevention." (PMID 33020545, 2020). "Correspondingly, an involvement of BDNF has been identified in the pathogenesis not only of T2DM, but also of dementia and depression." (PMID 33288788, 2020). "In addition, neuromuscular integrity and physical function are typically compromised in aging and dementia patients; thus, whether by stimulation of muscle-related growth factors or an increase in serum BDNF, FST supplementation may act to preserve physical function in the elderly." (PMID 30008787, 2018). "Elderly patients without dementia who participated in moderate aerobic training on the treadmill over six months had increased BDNF levels." (PMID 40869831, 2025). "The benefits of NT3 were reported in treating memory deficits, indicating its potential in inherited and acquired forms of dementias, which revealed that the pharmacological inhibition of HDAC3 increased BDNF expression and the potential role of NT3 in AD treatment using an NT3-transduced graft." (PMID 40732937, 2025). "Brain-derived neurotrophic factor (BDNF) plays a crucial role in cognitive functions and dementia." (PMID 41009553, 2025). "Therefore, this study investigates BDNF Val66Met genotypes, peripheral methylation at six BDNF regions, and BDNF mRNA and protein levels and correlates these variables with cognitive performance of individuals with MCI and dementia." (PMID 41009553, 2025). "Differences in DNA methylation of 6 chosen regions in BDNF promoters and exon IX were not statistically significant between individuals with dementia and MCI." (PMID 41009553, 2025). "It will be important that future studies replicate these results given that proteomics and BDNF, are not validated biomarkers in dementia diagnostics." (PMID 38237700, 2024). "Although everyone in the sample did not have a diagnosis of dementia, this indicates a potential effect of subtle cognitive changes on BDNF." (PMID 36970903, 2023). "First, Stein and colleagues showed small-to-moderate effects of 12 weeks’ AEx compared to usual-care control on resting plasma BDNF (SMD = 0.31, 95%CI [−0.45, 1.05]) and IGF-1 levels (SMD = −0.61, 95%CI [−1.29, 0.10]) in 34 participants with mild-to-moderate AD dementia." (PMID 39328309, 2023). "Findings from this study suggested that the effects of exercise on BDNF, irisin, IGF-1, and FGF-21 may be heterogeneous in older adults with mild-to-moderate AD dementia." (PMID 39328309, 2023). "Since sirtuin activity, brain-derived neurotrophic factor (BDNF) expression, and global DNA methylation levels significantly decrease in patients with PD or dementia, our group previously proposed the integration of these three epibiomarkers to improve NDD diagnostic accuracy." (PMID 36982820, 2023). "A study of 2131 elderly people without dementia showed that the higher the serum BDNF level, the lower the incidence of dementia." (PMID 35742280, 2022).
dementia (continued). "As a result, BDNF increased in the MCI stage and decreased in the dementia stage." (PMID 36425322, 2022). "BDNF expression is decreased in hippocampal and cortical neurons from 21-month APP/BIN1/COPS5 3xTg-AD mice, and is strongly reduced in buffy coat samples from patients with dementia or PD than in healthy control subjects." (PMID 35269588, 2022). "We postulate that there might be a dementia stage-dependent function of plasma BDNF; At the MCI stage, although cognitive functions have generally deteriorated, plasma BDNF is upregulated as a compensatory mechanism and is thus associated with worse cognition." (PMID 34607976, 2021). "To test our hypothesis, herein we analyzed human plasma EVs and NTF (CysC, PGRN, BDNF, and GDNF) in dementia patients (AD, DLB, and FTD diagnoses), investigating also the link between NTF and EVs." (PMID 34046409, 2021). "In our study, BDNF expression was almost non-existent in buffy coat samples obtained from patients suffering from various types of dementia, including AD and VaD." (PMID 35008438, 2021). "The combination of amyloid-beta deposits in the brain with both APOE ε4 and BDNF Met has been related to the steepest declines in memory and language cognitive domains in older individuals without dementia." (PMID 32218234, 2020). "It is reasonable to consider that healthy elderly subjects have different rates of physical activity compared to AD patients and that this influences BDNF levels irrespective of dementia." (PMID 29330839, 2018). "The main conclusion that can be drawn from this review is that result comparability and extension are critically impaired by the lack of control on factors that can influence circulating BDNF irrespective of dementia." (PMID 29330839, 2018). "Our results have shown altered BDNF and CREB expression levels in the hippocampus with dementia in rats, accompanied by the impairment of cognition in behavioral tests, which might be attributed to the reduction of cholinergic activity." (PMID 25231482, 2014). "Moreover, levels of BDNF are reduced in the entorhinal cortex in AD, and viral vector-mediated expression BDNF ameliorated memory and synaptic LTP deficits in a rat dementia model in which synapse-specific lesions were induced by botulinum toxin." (PMID 21331296, 2010). "(i) CSF BDNF decreased across the human life-span in the absence of dementia or MCI and was independent of inheritance of Met-BDNF or the APOE ε4 allele." (PMID 19412541, 2009). "While tDCS may induce synaptic plasticity and enhance neuronal viability through BDNF production, it has not yet been demonstrated to significantly slow progression to dementia." (PMID 40004217, 2025). "Given the comparable mean age of our elderly normal subjects without evidence of dementia to the glaucoma group, it suggests potential neuroprotective roles of BDNF Val66Met on retinal morphology under physiological conditions, especially regarding the temporal RNFL in older adults." (PMID 38916728, 2024). "In contrast, the neuroprotection of BDNF might not be enough to counteract brain damage in patients with dementia." (PMID 36674698, 2023). "Interestingly, we did not observe differences in BDNF concentrations in dementia patients compared to controls." (PMID 36674698, 2023). "The relationship between BDNF and WMH is not well studied, although one study found that number and volume of deep white matter lesions was positively associated with BDNF levels in patients without dementia." (PMID 36970903, 2023). "Therefore, the anti-dementia effect following ischemic stroke with metabolic syndrome of GCJ may involve the improvement of AChE, eNOS, BDNF, pERK/ERK, and neural plasticity." (PMID 37564141, 2023). "Furthermore, a protective effect of BDNF Val on episodic memory performance in older adults without dementia has been reported." (PMID 32218234, 2020).
dementia (continued). "In cohorts including subjective memory decline, MCI and dementia, the detrimental effects of amyloid positivity (for example, from fluid biomarkers or PET imaging) on brain connectivity (hippocampus to medial/frontal connectivity) were higher in BDNF Met carriers." (PMID 32218234, 2020). "Furthermore, brain-derived neurotrophic factor (BDNF), which functions in cortical neuron maintenance, has increased promoter CpG methylation in both AD brain tissue and blood, in support of similarities between methylation patterns in the blood and brain tissues of AD and other dementia patients." (PMID 38658973, 2024). "The study included 927 participants who had responded to the questionnaire on childhood adverse events, have DNA samples that could be used for analysis of BDNF methylation (i.e., provided blood samples and/or buccal swabs), and were without a diagnosis of dementia." (PMID 36911114, 2023). "Therefore, the relationship between serum BDNF levels and dementia is not clear and may be dependent on cognitive health and vary across normal and pathological cognitive aging trajectories." (PMID 34408648, 2021). "Interestingly, a correlation between BMI and circulating BDNF (positive for serum and negative for plasma) has been found in patients with eating and metabolic disorders, but little or no information is available for patients with dementia." (PMID 29330839, 2018). "BDNF Val66Met polymorphism was associated with methylation of the BDNF_IX amplicon, but not with methylation in BDNF promoters I and IV, peripheral BDNF gene and protein expression, neurocognitive symptoms detected with MMSE and CDT scales, or with dementia." (PMID 41009553, 2025). "BDNF Val66Met polymorphism was associated with methylation of the BDNF_IX amplicon, but not with methylation in BDNF promoters I and IV, peripheral BDNF gene and protein expression, MMSE and CDT scores, or dementia." (PMID 41009553, 2025). "They noted significantly lower plasma BDNF levels in patient group with both T2DM and dementia than in nondiabetic patients with dementia." (PMID 29062839, 2017). "In patients diagnosed with dementia, serum TNF-α and IL-1β were not correlated with BDNF levels." (PMID 33985854, 2021).